BCL6 (BCL6 transcription repressor)
Diseases named in the same sentence as BCL6 in open-access papers (continued):
Sharing a sentence is not in itself a finding about the gene and the disease.
lymphoma (continued). "The predominant type of lymphomas developed in UVRAGFS-expressing mice was diffuse large B cell lymphoma (DLBCL), which showed strong immunoreactivity for the B cell marker, CD20, but were negative for the germinal center marker Bcl-6." (PMID 31831743, 2019). "Because a satisfactory screening for rare cases of MYC/BCL6 DHL has not been defined so far, these flow cytometric findings might be helpful in triaging lymphomas for confirmatory targeted FISH analysis." (PMID 30323893, 2018). "Only in cases negative or doubtful for HGAL, BCL6 and CD10 could be added to exclude definitively lymphoma GC." (PMID 21988858, 2011). "In addition, all lymphomas developed in OPN-/-Faslpr/lpr mice were of the ABC-DLBCL type based on the expression of BCL2, C-MYC, IRF4 and of high proliferation rate (Ki67), in absence of BCL6." (PMID 36503430, 2022). "Moreover, BCL6 has a negative correlation with caspase-3 level in glioma tissues and it targeting PDCD2 to activate the caspase cascade results in the inhibition of apoptosis in lymphomas." (PMID 30420967, 2018). "However, prominent follicular colonization with numerous bcl-2+ lymphoma MALT cells may not be readily distinguished from the bcl-2+ neoplastic follicles of follicular lymphoma, and CD10 and bcl-6 may be difficult to interpret as either residual germinal centers or as lymphoma cells." (PMID 37958219, 2023).
B-cell lymphoma (299 papers, 2010 to 2026). "High-grade B-cell lymphomas expressing Myc, Bcl2, and Bcl6 proteins, known as “triple expressors,” are associated with aggressive behaviour and poor prognosis." (PMID 40941668, 2025). "Another example is the deregulated BCL6 expression which not only causes B-cell lymphoma development but also contributes to leukemia initiation." (PMID 38397429, 2024). "Alterations in BCL6 are mainly associated with B-cell lymphomas, however, in vitro upregulation of BCL6 has been identified as a possible regulator of response to therapy in EC through inhibition of transcription." (PMID 36376989, 2022). "For most patients with active B cell lymphomas, BCL6 is often expressed constitutively due to translocation of heterologous promoter elements or promoter point mutations in the BCL6 locus." (PMID 33216822, 2020). "A genome-wide association study of 253 Chinese individuals with B-cell NHL also identified a new susceptibility locus between BCL6 and LPP that was significantly associated with the increased risk of B-cell NHL." (PMID 32211398, 2020). "We underscore the critical importance of BCL6 and its associated epigenetic programs in the development of B-cell lymphoma, and discuss avenues for the therapeutic targeting of BCL6 in this context." (PMID 31788471, 2019). "In fact, re-expression of BAG6 and CBP/p300 upon inhibition of the transcriptional repressor BCL6 rendered B cell lymphoma cells and xenografts susceptible to HDACi and HSP90 therapy." (PMID 31534536, 2019). "The pharmacological inhibition of HDAC activity in B-cell lymphoma cells induces the accumulation of the inactive acetylated form of BCL6 causing cell cycle arrest and apoptosis." (PMID 30096875, 2018). "There are also suggestions that these agents can specifically cause apoptosis of BCL6 dependent B-cell lines and primary human B-cell lymphomas and this site on the BTB-POZ domain is, therefore, a validated target for drug discovery." (PMID 28929458, 2018). "The results show that the presence of BCL-6 mRNA is significantly associated with a high risk of death in B-cell lymphomas." (PMID 28881619, 2017). "The chromosomal translocations of Bcl6 regulatory region referred to as promoter substitution, and frequent mutations of the 5’ noncoding region of Bcl6 result in its deregulated expression, suggesting a key role for Bcl6 in pathogenesis of B-cell lymphoma." (PMID 28738086, 2017). "Immunohistochemistry for BCL6 is a part of the routine diagnostic work-up for B cell lymphoma, whereas pSTAT6 was suggested to be a marker for discriminating the PMBL group from other DLBCL subtypes." (PMID 23852366, 2013). "HCV infection has been reported to cause an approximately 5- to 10-fold increase in the mutation frequency of the Bcl6 gene in peripheral blood mononuclear cells, B-cell lymphoma cells, and their cell lines." (PMID 22395482, 2012). "BCL6 was originally discovered in B-cell lymphomas due to chromosomal translocations or mutations affecting this gene." (PMID 22870299, 2012). "In Ph+ ALL, light chain rearrangements are known to promote the expression of BCL6, a protein associated with survival and drug resistance, whereas in B cell lymphomas, active BCR signaling has been shown to drive tumorigenesis and support leukemia cell survival." (PMID 40634509, 2025). "Importantly, genetic alterations or dysregulation of BCL6 is associated with the development of B-cell lymphomas." (PMID 38864622, 2024). "BCL6 is the product of a proto-oncogene implicated in the pathogenesis of human B-cell lymphomas." (PMID 38864622, 2024). "Another example of a novel BAP1-regulated gene identified in our work is Litaf, which encodes a repressor of Bcl6-expression and a regulator of autophagy in B cell lymphoma, and indeed autophagy plays an important role in the regulation of GC reaction and plasma cell maintenance." (PMID 38529289, 2024).
B-cell lymphoma (continued). "Remarkably, mutations in BCL6 could result in the development of B cell lymphomas that could be owing to unchecked B cell growth, therefor such mutations could be used as diagnostic markers for B cell lymphomas and other cancers." (PMID 39564119, 2024). "Initially described as a proto-oncogene and transcriptional repressor implicated in the pathogenesis of B-cell lymphoma, BCL6 has recently been identified as a promising tissular biomarker which could be used to diagnose women affected by endometriosis." (PMID 36294483, 2022). "Other mutation hot-spots in B-cell lymphoma were the enhancers of BCL6, BCL2 and ST6GAL1." (PMID 34210001, 2021). "BCL6, a germinal center-associated antigen, is a transcription factor and master regulator of B cell differentiation in germinal center B cells and thus is characteristically found in B cell lymphomas of germinal center origin." (PMID 29545910, 2018). "Of note, BCL6 upregulation is also associated with the development of B-cell lymphomas in humans." (PMID 29379791, 2017). "In addition, elevated BCL6 expression is associated with B-cell lymphoma development in mice and TAX is associated with the accumulation of DNA damage and can induce transformation in vitro." (PMID 29379791, 2017). "BCL6 is a proto-oncogene located on chromosome 3q27 that encodes a transcriptional repressor that was originally characterized as a regulator of B-lymphocyte development and growth and has been indicated in the pathogenesis of B-cell lymphoma." (PMID 25009651, 2014). "Furthermore, LITAF might facilitate cell apoptosis and terminal differentiation by transcriptional repression of BCL6, thereby increasing the likelihood of other genetic events associated with the development of B-cell lymphomas." (PMID 27764808, 2016). "FISH analysis of a large B-cell lymphoma revealed an atypical BCL6 rearrangement with a 1G1F signal pattern and an IGH::BCL2 fusion." (PMID 41010038, 2025). "FBXO11 promotes the degradation of BCL6 in B-cell lymphoma through ubiquitination, playing a critical role in regulating BCL6 protein levels." (PMID 40534867, 2025). "BCL6, a transcriptional repressor imbued with anti-apoptotic and oncogenic attributes, was initially identified as an oncogene within Non-Hodgkin's B-Cell Lymphoma." (PMID 40066352, 2025). "Both IGH and RHOH are highly expressed in normal B cells indicating that the merger of the BCL6 SS domain with SE regions potentially represents a functional explanation for the aberrant upregulation of BCL6 in B-cell lymphoma." (PMID 40998810, 2025). "Since the discovery of BCL6 as an important oncogene in B cell lymphoma formation, initial studies focused on treating B cell malignancies using BCL6 inhibition." (PMID 41246349, 2025). "Blockade of BCL6 by inhibitory compounds has emerged as a promising therapeutic strategy in the treatment of BCL6-expressing B cell lymphomas." (PMID 41246349, 2025). "Both IGH and RHOH are highly expressed in normal B cells, indicating that the merger of the BCL6 SS domain with SE regions represents a potential functional explanation for the aberrant upregulation of BCL6 in B-cell lymphoma." (PMID 40631184, 2025). "Conventional cytogenetics analysis identifies patients with translocation of MYC and BCL2 and/or BCL6 as a subgroup of aggressive B-cell lymphoma with poor prognosis and phenotypic proximity to Burkitt lymphoma." (PMID 41364305, 2025). "Originally identified as a proto‐oncogene in B‐cell lymphomas, BCL6 drives malignant phenotypes by repressing proliferation and DNA damage checkpoints, as well as by blocking terminal B‐cell differentiation." (PMID 41438489, 2025).
B-cell lymphoma (continued). "To validate that B-cell lymphoma development in Fbw7ΔEC mice was BCL6-dependent, we performed adoptive transfer experiments using freshly isolated DLBCL cells from Fbw7ΔEC mice." (PMID 38485719, 2024). "Since the early discoveries of ZBTB16 in APL and BCL6 in B-cell lymphomas and leukemias, an increasing number of studies have focused on the roles of ZBTB proteins in hematological malignancies." (PMID 38397429, 2024). "Three specimens of 182 (1.6%) showed MYC and BCL6 rearrangements, which according to the ICC, is diagnostic of the provisional entity high-grade B-cell lymphoma with MYC and BCL6 rearrangements." (PMID 38903717, 2024). "For example, in B cell lymphoma, the use of BCL6 inhibitors relieved the BCL6-mediated repression of BCL2, leading to addiction to this oncogene." (PMID 39456751, 2024). "We delve into its potential to induce apoptosis in B-cell lymphomas that rely on Bcl6 for survival, highlighting its relevance in the realm of hematologic cancers." (PMID 39564119, 2024). "Its capacity to induce apoptosis in B-cell lymphomas dependent on Bcl6 for survival underscores its relevance in hematologic cancers." (PMID 39564119, 2024). "All cases were successfully tested for common breakapart molecular events for B-cell lymphomas and PCNLs, BCL6, BCL2, CCND1, IGH, IGL, IGK, and MYC." (PMID 38730692, 2024). "Zanubrutinib is a BTK inhibitor reported to be effective for B‐cell lymphomas with MYD88 and CD79b mutations, double expression of MYC and BCL2/BCL6, and CD5 expression." (PMID 39054569, 2024). "GC B-cells represent the normal counterpart of most human B-cell lymphomas, which are often characterized by upregulated BCL6 expression and BCL6-mediated pathways." (PMID 37047075, 2023). "We therefore performed GST pull-down assays for NFAT, NF-κB p65, c-Jun, and BCL6, which are reported to be important TFs in B-cell lymphomas." (PMID 38089883, 2023). "Major changes have been made in the diffuse large B-cell lymphomas (DLBCL)/high-grade B-cell lymphomas (HGBL) associated with MYC and BCL2 and/or BCL6 rearrangements." (PMID 37190213, 2023). "B-cell lymphoma 6 protein (BCL-6) was first identified as an oncogene important for proliferation in B-cell lymphomas but was later found in various tumors, as well as endometrial pathologies." (PMID 37174948, 2023). "While aberrant activation of miR10a reduced BCL6 in B-cell lymphoma, the role of HOXB5 remained unclear." (PMID 37371852, 2023). "Major oncogenes frequently associated with particular types of B-cell lymphoma are BCL2 (FL, DLBCL), BCL6 (DLBCL), CCND1 (MCL, MM), and MYC (BL, DLBCL)." (PMID 37371852, 2023). "High-grade B-cell lymphoma with translocations of MYC and BCL2 and/or BCL6 genes has been associated with a worse prognosis, whereas mutations such as MYD88 and CD79B have been frequently described in PCNSL." (PMID 37240953, 2023). "It is especially interesting to examine the effect of AL928768.3 eRNA in the regulation of other oncogenes (CCND1, BCL-6) that are translocated into the IGH locus as a result of chromosomal rearrangements in B-cell lymphomas." (PMID 35563017, 2022). "BCL6 was initially identified as an oncogene in B-cell lymphomas, with this gene thought to drive the malignant phenotype by repressing proliferation and DNA damage checkpoints and blocking B-cell terminal differentiation." (PMID 35721059, 2022). "In our study, the third case demonstrated a relapse within the eye after an initial systemic high-grade B-cell lymphoma with MYc and BCL6 rearrangements which was in complete remission as a result of allo and auto hematopoietic stem cell transplantations." (PMID 35334633, 2022). "Cytogenetic FISH testing for rearrangements of MYC and BCL2 and/or BCL6, helps to identify double-hit or triple-hit, high grade B-cell lymphoma with even poorer outcome and the need for more intensive treatment plans." (PMID 35626243, 2022).
B-cell lymphoma (continued). "Currently, Bcl-6 is already a cancer therapeutic target in B-cell lymphomas, and Bcl-6 degraders find their way to the clinic." (PMID 35625998, 2022). "The B-cell lymphoma 6 (BCL6) gene, initially found in B-cell lymphoma as a proto-oncogene, drives the malignant phenotype by inhibiting gene transcription and DNA damage checkpoints and blocking B-cell terminal differentiation." (PMID 35883106, 2022). "BCL6 is a transcriptional repressor with anti-apoptotic and pro-oncogenic properties that was initially identified as an oncogene in non-Hodgkin’s B-cell lymphoma." (PMID 36704339, 2022). "High-grade B-cell lymphomas (HGBLs), with c-Myc, Bcl2, and/or Bcl6 rearrangement, are aggressive neoplasms with poor clinical outcomes." (PMID 36312606, 2022). "HGBL-DH/TH (high grade B-cell lymphoma with double/triple hits) harbor simultaneous translocations of MYC and BCL2 (DHL BCL2) or MYC and BCL6 (DHL BCL6), which associate with aggressive clinical course and inferior prognosis." (PMID 35884496, 2022). "BCL6 overexpression was shown to inhibit oxidative stress responses to chemotherapeutic reagents in B-cell lymphoma cells, and BCL6 knockdown increased hypoxia-induced oxidative stress in cardiomyocytes." (PMID 36432475, 2022). "Most B-cell lymphomas occurring in germinal center (GC) B cells require continuous expression of BCL6 for survival." (PMID 35883106, 2022). "BCL6 (B-cell lymphoma 6) is a proto-oncogene and transcriptional repressor initially described as being involved in B-cell lymphoma." (PMID 36294483, 2022). "The translocations of MYC and BCL2 and/or BCL6 in patients with high-grade B-cell lymphomas remained a significant independent predictor of a poorer PFS and OS, but the standard of care for these patients has not been established." (PMID 35153779, 2022). "The WHO classification of lymphoid neoplasms further categorizes HGBL with the addition of a new term, "high-grade B-cell lymphoma with c-Myc, Bcl2, and/or Bcl6 rearrangement"." (PMID 36312606, 2022). "Bcl-6, encoded by the BCL6 gene, was initially discovered as an oncogene in B-cell lymphomas, driving a malignant phenotype via the repression of DNA damage and proliferation checkpoints." (PMID 35163005, 2022). "BCL6 was initially discovered as an oncogene in B-cell lymphomas and consequently emerged as a therapeutic target." (PMID 33468080, 2021). "Together, these results suggest only subtle effects of BCL6 inhibition in our panel of B-cell lymphoma cell lines." (PMID 34274316, 2021). "Overexpression of the BCL6 inhibits chemotherapy-induced ROS production and apoptosis in B-cell lymphoma cells." (PMID 33541426, 2021). "This molecule did not have degrader activity and had little activity in reducing viability or suppressing growth of B-cell lymphoma cell lines that expressed BCL6." (PMID 34274316, 2021). "Various spontaneous tumor models (such as the Eμ-Myc, Eμ-BRD2, or Bcl6 mouse models) have been developed to study how B-cell lymphomas arise and mature in different tumor environments." (PMID 34207773, 2021). "Bcl-6 activity can be deregulated by a variety of mechanisms and contributes to the development of B-cell lymphoma." (PMID 33412518, 2021). "The BCL6 gene is an oncogene involved in B-cell lymphoma, which can drive malignant phenotypes by inhibiting DNA damage checkpoints and blocking B-cell terminal differentiation." (PMID 33541426, 2021). "Previous studies found that HSP90 can interact with B-cell Lymphoma 6 (Bcl-6) and maintained the stability of its mRNA, which was required to the survival of B-cell lymphomas cells." (PMID 34956178, 2021). "When MYC translocation occurs simultaneously with BCL2 and/or BCL6, the cases are classified as DH/TH high-grade B-cell lymphoma." (PMID 34207773, 2021). "Both BCL6 peptide inhibitors and small molecule inhibitors have been shown to have potent efficacy against B-cell lymphoma cells and BCL6-dependent DLBCL cell lines." (PMID 34207773, 2021).